PHF19 (PHD finger protein 19)
Diseases named in the same sentence as PHF19 in open-access papers (continued):
Sharing a sentence is not in itself a finding about the gene and the disease.
endometriosis (1 paper, 2021). The growth of functional endometrial tissue in anatomic sites outside the uterine body. "Putting these results together with miR-155 transfection studies, this study suggests that while miR-155 and PHF19 may be the main helper in regulating the PRC2 complex in endometriosis, JARID2 may be taking up the slack when miR-155 is inhibited." (PMID 33800594, 2021). "This may suggest that miR-155 and PHF19 may be working together to bring the PRC2 complex to its targets in endometriosis." (PMID 33800594, 2021). "Additionally, the role for PHF19 as the master-regulator of the miR-155-PRC2 complex-JARID2 crosstalk is also a viable candidate for therapy and should be further explored in endometriosis." (PMID 33800594, 2021).
lung adenocarcinoma (1 paper, 2022). A carcinoma that arises from the lung and is characterized by the presence of malignant glandular epithelial cells. "As previously reported, hsa_circ_0002360 (parental RUNX1) overexpressed in lung adenocarcinoma and hsa_circ_000-2360/hsa-mir-3620-5p/PHF19 might interact in the progression of lung adenocarcinoma under cicrRNA-miRNA-mRNA networks." (PMID 35123506, 2022).
myeloid leukemia (1 paper, 2021). A clonal proliferation of myeloid cells and their precursors in the bone marrow, peripheral blood, and spleen. "In this study, we demonstrated not only the antiproliferative effects of targeting PHF19 in myeloid leukemias but also how its reduction leads to specific differentiation of CML cells toward the erythroid pathway." (PMID 33996816, 2021). "In particular, myeloid leukemia cell lines show increased levels of PHF19, yet little is known about its function." (PMID 33996816, 2021). "Here, we have characterized the role of PHF19 in myeloid leukemia cells." (PMID 33996816, 2021). "Taken together, our results show that PHF19 is a key transcriptional regulator for cell fate determination and could be a potential therapeutic target for myeloid leukemia treatment." (PMID 33996816, 2021). "Therefore, the role of PHF19 in myeloid leukemias, which are a clear example of the accumulation of undifferentiated progenitors, needs to be further investigated." (PMID 33996816, 2021).
ovarian tumor (1 paper, 2020). "This study is the first to report the role of PHF19 in the anti-ovarian tumor effect of CFG." (PMID 32180719, 2020).
polyp (1 paper, 2025). A usually exophytic mass attached to the underlying tissue by a broad base or a thin stalk. "Furthermore, polyp samples exhibited significantly higher PHF19-207 expression compared to healthy mucosa (p = 0.035)." (PMID 40563408, 2025).
prostate adenocarcinoma (1 paper, 2021). "Meanwhile, PHF19 expression was markedly decreased in KICH (kidney chromophobe), PRAD (prostate adenocarcinoma), and UCEC (uterine corpus) than in their respective normal samples." (PMID 35069553, 2021).
Splenomegaly (1 paper, 2021). Abnormal increased size of the spleen. "Young constitutive Phf19-deficient mice exhibit normal T cell development and homeostasis, however, aged Phf19-deficient mice (>60 weeks) have a high penetrance of splenomegaly." (PMID 34857028, 2021).
uveal melanoma (1 paper, 2021). A melanoma derived from melanocytes of the uveal tract. "High transcriptional levels of PHF19 were linked to unfavorable prognosis in OS of ACC, LIHC, MESO, and SKCM, and DFS analysis data showed that elevated PHF19 level was related to unfavorable prognosis for ACC, LGG, LIHC, and UVM (uveal melanoma) (all log-rank P values < 0.05)." (PMID 35069553, 2021).
cancer (30 papers, 2012 to 2025). A tumor composed of atypical neoplastic, often pleomorphic cells that invade other tissues. "We inspected the genomic alterations and mutation profiles of PHF19 in the TCGA cancer cohorts by employing the cBioPortal database." (PMID 35069553, 2021). "The dysregulation of PHF19 expression is associated with the development of several cancers, including GC." (PMID 34078310, 2021). "The expression of PHF19 is also significantly associated with tumor mutation burden and microsatellite instability, suggesting a potential role in the modulation of immune response to cancer." (PMID 38813086, 2024). "Meanwhile, since TMB and MSI are regarded as critical factors impacting on oncogenesis and progression of tumors, and affecting response to immunotherapy in cancers, we next performed association analyses between PHF19 expression and TMB/MSI spanning all TCGA tumor types." (PMID 35069553, 2021). "Taken together, the present study unveiled the complicated roles of PHF19 aberrant expression in the progression and prognoses of cancers, and summarized the pivotal signaling pathways associated with the pathophysiological functions of this epigenetic related gene." (PMID 35069553, 2021). "The PHF19 gene encodes the PHD finger protein 19 (PHF19), which has been shown to play a tumor-promoting role in several cancer types, including CRC." (PMID 40563408, 2025). "The PHF19-207 transcript, produced by the promoter upregulated in cancer, was examined using various in silico tools to assess its potential function." (PMID 40723829, 2025). "Since NFI/CTF transcription factors have both oncogenic and tumor suppressor potential, depending on the type of carcinoma, their role in regulating PHF19 gene promoters should be further investigated." (PMID 40723829, 2025). "PHF19, a key component of PRC2, is identified as an epigenetic regulator implicated in various cancers, including HCC." (PMID 38813086, 2024). "Conversely, PHF19 (PHD finger protein 19) exhibited increased expression of the intronic APA transcript (ENST00000312189.10) in tumor samples from nine different cancer types." (PMID 39349823, 2024). "The relevance of PHF19 in this cancer type is also supported by computational approaches, functional assays, and patient data." (PMID 37107696, 2023). "The super-enhancer at PHF19 likely drives a high expression of PHF19 in this cancer type, required for efficient tumor growth." (PMID 37107696, 2023). "In this cancer type, PHF19 is required for setting up PRC2-dependent broad H3K27me3 domains, which is important for the optimal silencing of PRC2 target genes." (PMID 37107696, 2023). "Studies have shown that LINC_00355 increases PHF19 expression, which targets miR-15a-5p downstream, resulting in the proliferation, transmission, and attack of cancer cells." (PMID 37361568, 2023). "In contrast to PHF1 and MTF2, PHF19 has primarily been described as an oncogene in multiple cancer types." (PMID 37107696, 2023). "PHF1 is predominantly downregulated in cancer, while PHF19 is largely upregulated, implicating a potentially opposing role of these two proteins." (PMID 37107696, 2023). "PHF19 is relevant not only in the cancer cells themselves but also in cells involved in the fight against cancer." (PMID 37107696, 2023). "In summary, most studies on the role of PCL proteins in cancer refer to the oncogenic role of PHF19 in a variety of cancers and PHF1 gene translocations in endometrial stromal sarcoma and ossifying fibromyxoid tumors." (PMID 37107696, 2023). "In the following, we will address the known roles of PHF1, MTF2, and PHF19 in cancer and the possible mechanisms involved." (PMID 37107696, 2023). "PHF19 was discovered as a tumor-promoting gene in various cancers, including LUAD, but the in-depth molecular mechanism has yet to be studied." (PMID 36263018, 2022).
cancer (continued). "Given that PHF19 expression correlates with TMB and MSI which affect response to cancer immunotherapy, we next explored the correlations between PHF19 expression level and the abundance of immune cell infiltrates." (PMID 35069553, 2021). "Collectively, as a critical epigenetic related gene, PHF19’s potential roles in carcinogenesis and cancer development are worthwhile to be disclosed." (PMID 35069553, 2021). "Our study suggests that PHF19 can serve as a carcinogenic indicator related to prognosis in pan-cancer, especially HCC, and shed new light on therapeutics of cancers for clinicians." (PMID 35069553, 2021). "Intriguingly, PHF19 expression was also positively relevant to the infiltration abundance of CD4+ Th1 cells in 18 cancer types, with all correlation coefficients < 0.45, and negatively relevant to that in PRAD, with the correlation coefficient = -0.29." (PMID 35069553, 2021). "Compared with corresponding noncancerous tissues, PHF19 expression was significantly up-regulated across a range of cancers, which implied the extensively oncogenic characteristics of PHF19 in cancers and promising perspectives in the field of cancer research." (PMID 35069553, 2021). "In the present study, we explored the pan-cancer expression profiles of PHF19, and the correlation between PHF19 aberrant expression and patient prognosis in different cancers." (PMID 35069553, 2021). "To further evaluate the expression status of PHF19 spanning various cancer types, we analyzed the TCGA RNA sequencing data by applying the TIMER2.0 approach." (PMID 35069553, 2021). "Deregulations of PHD finger protein 19 (PHF19) and enhancer of zeste 2 (Ezh2) implied in epigenetic regulation have been frequently associated with cancers." (PMID 35003347, 2021). "While these findings warrant further investigation, our research provides novel insights into the promising application prospects of PHF19 in the field of cancer research." (PMID 35069553, 2021). "High PHF19 levels were critically associated with the infiltration of myeloid-derived suppressor cells (MDSCs) and Th2 subsets of CD4+ T cells in most cancers." (PMID 35069553, 2021). "We investigated the expression patterns of PHF19 in normal tissues, various cell lines and cancers, and estimated the prognostic values of PHF19 in pan-cancer based on multiple databases." (PMID 35069553, 2021). "The present research was primarily designed to provide the prognostic landscape visualizations of PHF19 in cancers, and study the correlations between PHF19 expression and immune infiltration characteristics in tumor microenvironment." (PMID 35069553, 2021). "Currently, the transcriptional, post-transcriptional and post-translational regulation of PHF19 in normal and cancer cells is underexplored; however, some insights are available from cancer cells." (PMID 34857028, 2021). "Increased expression of PHF19 was detrimental to the clinical prognoses of cancer patients, especially HCC." (PMID 35069553, 2021). "PHD finger protein 19 (PHF19) is an associated factor of Polycomb repressor complex 2 (PRC2), often upregulated in human cancers." (PMID 33996816, 2021). "PHF19 KD experiments in several cancer cellular models shows the downregulation and de-repression of the expression of a significant number of PRC2-target genes, however, a number of genes have no detectable change in expression." (PMID 34857028, 2021). "Human PHF19 gene was first identified in 2004 and its products are markedly overexpressed in many types of cancers, including colon, skin, lung, rectal cervical, uterus, and liver cancers." (PMID 32180719, 2020). "In humans, PHF19 encodes a long (PHF19L) and a short (PHF19S) isoform, that are generated by alternative splicing and are both overexpressed in a wide variety of cancers." (PMID 32155117, 2020). "Previous studies have shown that PHF19 plays important roles in cancer progression, including cell cycle regulation, proliferation, invasion, and drug resistance." (PMID 30323224, 2018).
cancer (continued). "Recently, several studies have confirmed that PHF19 is upregulated in many types of cancer tissues compared with the corresponding normal tissues." (PMID 30323224, 2018). "Understanding whether the PHF19-207 transcript exerts a regulatory function in cancer-related cellular processes could shed light on its biological role and reveal whether its modulation may have therapeutic potential." (PMID 40563408, 2025). "The upregulation of PHF19 in cancers correlates with increased immune cell infiltration, particularly of myeloid-derived suppressor cells and Th2 subsets of CD4+ T cells, which may contribute to the immune evasion mechanisms of tumors." (PMID 38813086, 2024). "Many malignant tumors are affected by PHF19, which has a significant effect on prognosis." (PMID 38212708, 2024). "To date, the most compelling role of PHF19 in cancer has been found in multiple myomas (MM)." (PMID 37107696, 2023). "Indeed, when looking at all cancer types, high PHF1 expression is associated with a better prognosis, while high PHF19 expression is typically linked to a worse outcome." (PMID 37107696, 2023). "Therefore, we foresee a model where high levels of PHF19 in CML cancer cells would lead to small albeit enough accumulation in other genomic targets." (PMID 33996816, 2021). "We also demonstrated that PHF19 played important roles in regulating tumor-infiltration of immune cells, and might exhibit beneficial therapeutic effects on cancer treatment." (PMID 35069553, 2021). "The increased PHF19 expression correlates with advanced cancers." (PMID 35003347, 2021). "We next retrieved PHF19 mRNA expression levels over a cancer-wide range via the ONCOMINE database." (PMID 35069553, 2021). "We examined the expression patterns, prognostic values, mutation landscapes, and protein-protein interaction network of PHF19 in pan-cancer utilizing multiple databases, and investigated the relationship of PHF19 expression with immune infiltrates across TCGA-sequenced cancers." (PMID 35069553, 2021). "The findings highlight the positive regulatory role of PHF19 in cancer development." (PMID 34078310, 2021). "In the last few years, several reports have addressed the role of PHF19 in different types of cancers, including melanoma, prostate, glioblastoma, and also hematopoietic malignancies of the lymphoid branch, such as multiple myeloma, as well as its specific role in preventing T cell exhaustion." (PMID 33996816, 2021). "In addition to the marker analyses, we also examined the effect of PHF19 expression changes on the self-renewal ability of cancer stem cells using sphere formation assay." (PMID 32180719, 2020). "Likewise, PHF19 is frequently up regulated in several types of cancer including human breast IDC, ILC and DCIS and is associated with tumor progression." (PMID 23131872, 2012). "The interaction between the tumor and stroma, along with the contribution of immune cells to the cancer microenvironment, could further influence its expression, making the PHF19-207 transcript a complex marker shaped not only by tumor cells but also by the surrounding tissue environment." (PMID 40563408, 2025). "However, the exact roles of PHF19 in cancers remain enigmatic." (PMID 35069553, 2021). "Finally, we validated pan-cancer PHF19 expression, and its impacts on immune infiltrates in HCC." (PMID 35069553, 2021). "Besides, we explored the links between PHF19 expression and tumor mutation burden (TMB), microsatellite instability (MSI), immune checkpoints and immune infiltration, and identified the specific genes and signaling pathways involved in the regulation of cancer development by PHF19." (PMID 35069553, 2021). "Initially, PHF19 was identified as a gene similar to Drosophila PCL, which shows elevated expression levels in cancer." (PMID 37107696, 2023).
cancer (continued). "Overexpression of PHF19 can promote the migration, invasion, and proliferation of HCC cells in vitro and participate in the regulation of the expression of cancer-related proteins." (PMID 34163524, 2021). "Here the authors show that a microRNA, miR-155, suppresses Ship1 phosphatase expression to modulate epigenetic reprogramming of CD8 T cell differentiation via the Phf19/PRC2 axis, thereby implicating a novel aspect of cancer immunity regulation." (PMID 31089138, 2019). "Recent findings from an extensive pan-cancer transcriptome analysis revealed differential expression of two alternative PHF19 gene promoters in malignant versus non-malignant gut mucosa." (PMID 40723829, 2025). "Recent pan-cancer transcriptome analysis has revealed differential activity of two alternative PHF19 gene promoters in malignant versus non-malignant gut mucosa." (PMID 40723829, 2025). "Currently, many studies regarding PHF19 in cancer do not fully distinguish between these two isoforms, making the conclusion about the role of PHF19 in cancer less defined." (PMID 37107696, 2023). "Thus, although these data globally support a tumor-suppressive role of PHF1, an oncogenic role of PHF19, and a relatively neutral role of MTF2, the three PCL proteins appear to have individual impacts dependent on the cancer type." (PMID 37107696, 2023). "There were significant correlations between PHF19 expression and TMB or MSI in several cancers." (PMID 35069553, 2021). "On balance, PHF19 expression was significantly higher in cancers in comparison with that in noncancerous samples." (PMID 35069553, 2021). "The heatmap exhibited that PHF19 expression was positively and statistically significantly correlated with the immune infiltration of myeloid-derived suppressor cells (MDSCs) and Th2 subset of CD4+ T cells in the majority of cancers." (PMID 35069553, 2021). "The authors demonstrated that CD8+ T-cell differentiation is regulated through the miR-155–Phf19 (PHD Finger Protein 19)–PRC2 (polycomb repressive complex 2) axis, paving the way for new methods for potentiating cancer immunotherapy through epigenetic reprogramming of CD8+ T-cell fate." (PMID 34359591, 2021). "PHF19 has been proved to be closely related to the prognosis of patients in a variety of malignant tumors, but the effect of PHF19 on the prognosis evaluation of CRC patients has not been confirmed." (PMID 34141488, 2021). "Our initial exploration demonstrated that aberrant PHF19 expression was correlated with increased immune cell infiltration of MDSCs and Th2 subset of CD4+ T cells in the majority of cancers, which implied potential value of clinical application for PHF19 in cancer treatment." (PMID 35069553, 2021). "In consequence, the present study points new directions for delineating the relationships between the epigenetic related PHF19 gene and immune cell infiltration within the TME, which may have important implications for exploring new strategies for cancer therapy." (PMID 35069553, 2021). "However, despite these efforts to understand the role of PHF19 in different cancer models, a comprehensive analysis that identifies the genetic targets and pathways controlled by PHF19 has so far not been reported." (PMID 32155117, 2020). "Our analyses revealed that certain genes, such as PHF19 and VRK3, which are truncated in 9 and 5 different cancers, respectively, exhibit a negative correlation between the TR and disease-free survival time or survival rate in specific cancer types." (PMID 39349823, 2024).